PSMD11 (proteasome 26S subunit, non-ATPase 11)
Description:
Component of the 26S proteasome, a multiprotein complex involved in the ATP-dependent degradation of ubiquitinated proteins. This complex plays a key role in the maintenance of protein homeostasis by removing misfolded or damaged proteins, which could impair cellular functions, and by removing proteins whose functions are no longer required. Therefore, the proteasome participates in numerous cellular processes, including cell cycle progression, apoptosis, or DNA damage repair. In the complex, PSMD11 is required for proteasome assembly. Plays a key role in increased proteasome activity in embryonic stem cells (ESCs): its high expression in ESCs promotes enhanced assembly of the 26S proteasome, followed by higher proteasome activity.
Synonyms: S9; p44.5; MGC3844; Rpn6
Tractability: Small molecule: an approved drug acts on it; a structure with a bound ligand is known; a high-quality ligand is known. Antibody: its Gene Ontology location is reachable by antibodies, with high confidence. PROTAC: UniProt records ubiquitination sites on it; ubiquitination databases record sites on it; its protein half-life has been measured; a small molecule that binds it is known.
Target class: Enzyme
Gene: Protein-coding gene on chromosome 17 (32,444,379 to 32,483,319, forward strand). Ensembl gene ENSG00000108671.
Subcellular location: Nucleus; Cytoplasm, cytosol
Subcellular location (Human Protein Atlas): Golgi apparatus; Nucleoplasm; Perinuclear theca; Principal piece
Pathways (Reactome):
Immune System: AMPK-induced ERAD and lysosome mediated degradation of PD-L1(CD274); Activation of NF-kappaB in B cells; Antigen processing: Ubiquitination & Proteasome degradation; CLEC7A (Dectin-1) signaling; Cross-presentation of soluble exogenous antigens (endosomes); Dectin-1 mediated noncanonical NF-kB signaling; Downstream TCR signaling; ER-Phagosome pathway; FCERI mediated NF-kB activation; GSK3B-mediated proteasomal degradation of PD-L1(CD274); Interleukin-1 signaling; NIK-->noncanonical NF-kB signaling; Neutrophil degranulation; SPOP-mediated proteasomal degradation of PD-L1(CD274); TNFR2 non-canonical NF-kB pathway
Cell Cycle: APC/C:Cdc20 mediated degradation of Securin; APC/C:Cdh1 mediated degradation of Cdc20 and other APC/C:Cdh1 targeted proteins in late mitosis/early G1; Autodegradation of Cdh1 by Cdh1:APC/C; Autodegradation of the E3 ubiquitin ligase COP1; Cdc20:Phospho-APC/C mediated degradation of Cyclin A; FBXL7 down-regulates AURKA during mitotic entry and in early mitosis; G2/M Checkpoints; SCF(Skp2)-mediated degradation of p27/p21; SCF-beta-TrCP mediated degradation of Emi1; Separation of Sister Chromatids; The role of GTSE1 in G2/M progression after G2 checkpoint; Ubiquitin-Mediated Degradation of Phosphorylated Cdc25A; Ubiquitin-dependent degradation of Cyclin D
Signal Transduction: Asymmetric localization of PCP proteins; Degradation of AXIN; Degradation of DVL; Degradation of GLI1 by the proteasome; Degradation of GLI2 by the proteasome; Degradation of beta-catenin by the destruction complex; GLI3 is processed to GLI3R by the proteasome; Hedgehog 'on' state; Hedgehog ligand biogenesis; MAPK6/MAPK4 signaling; Negative regulation of NOTCH4 signaling; Regulation of PTEN stability and activity
and 28 more pathways
Gene Ontology:
Molecular function: protein binding; structural molecule activity
Biological process: proteasome assembly; stem cell differentiation; ubiquitin-dependent protein catabolic process; cellular response to type I interferon; proteasomal protein catabolic process; proteasome-mediated ubiquitin-dependent protein catabolic process; regulation of proteasomal protein catabolic process; response to oxidative stress
Cellular component: membrane; nucleus; proteasome accessory complex; proteasome complex; cytosol; extracellular region; ficolin-1-rich granule lumen; nucleoplasm; proteasome regulatory particle, lid subcomplex; secretory granule lumen; synaptic vesicle; proteasome regulatory particle; protein-containing complex
Genetic constraint (gnomAD): Loss-of-function variants: 1 observed, 58.01 expected, observed/expected ratio (o/e) 0.0172, 90% interval 0.005 to 0.082. The upper end of that interval is the gene's LOEUF score, 0.082, which puts it in group 1 of 6, group 1 being the genes least tolerant of losing a copy. Missense variants: 292 observed, 513.55 expected, observed/expected ratio (o/e) 0.57, 90% interval 0.52 to 0.63. Synonymous variants: 181 observed, 195.34 expected, observed/expected ratio (o/e) 0.93, 90% interval 0.82 to 1.05.
Homologues: Orthologues: chimpanzee PSMD11 (100% identical), guinea pig PSMD11 (100% identical), macaque PSMD11 (100% identical), rabbit PSMD11 (100% identical), rat Psmd11 (100% identical), mouse Psmd11 (99% identical), pig PSMD11 (99% identical), tropical clawed frog PSMD11 (95% identical), zebrafish psmd11a (94% identical), zebrafish psmd11b (91% identical), dog PSMD11 (86% identical), Drosophila melanogaster Rpn6 (68% identical), and 2 more. Paralogues in human: COPS2 (26% identical).
Diseases named in the same sentence as PSMD11 in open-access papers:
PSMD11 is named in the same sentence as 29 diseases in open-access papers, as found by Europe PMC text mining. Sharing a sentence is not in itself a finding about the gene and the disease. The quoted sentences say what the papers report.
pancreatic cancer (9 papers, 2019 to 2025). "Accordingly, high levels of PSMD11 are associated with poorer overall survival and were found in plasma-derived microparticles of pancreatic cancer patients with poor prognosis." (PMID 35565454, 2022). "Since the expression of PSMD11 and PSMD14 in pancreatic cancer tissues was significantly higher than that in normal tissues, we hypothesized that PSMD11 and PSMD14 might have diagnostic and prognostic value in pancreatic cancer." (PMID 40182048, 2025). "In conclusion, this study revealed the important roles of PSMD11 and PSMD14 in pancreatic cancer and provided insights into their underlying mechanisms." (PMID 40182048, 2025). "For example, small interfering RNA (siRNA)-mediated knockdown of PSMD11 triggered acute apoptosis in pancreatic cancer cells, suggesting that PSMD11 is a promising target for cancer therapy." (PMID 40182048, 2025). "Studies have revealed that PSMD11 serves as a potential biomarker for predicting the progression of pancreatic cancer." (PMID 38482057, 2024). "Next, we examined the effects of PSMD11 on pancreatic cancer migration and invasion in vitro." (PMID 40182048, 2025). "PSMD11 is a novel biomarker of pancreatic cancer progression." (PMID 34839279, 2021). "For it had been shown that knockdown of PSMD11 by siRNA could promote acute apoptosis in pancreatic cancer cells, we also detected if depletion of PSMD11 could induce apoptosis in MEFs." (PMID 33517884, 2021). "In conclusion, the mRNA expression levels of PSMD11 and PSMD14 were significantly higher in pancreatic cancer tissues compared with normal pancreatic tissues." (PMID 40182048, 2025). "We found that PSMD11 and PSMD14 mRNA expression was significantly upregulated in pancreatic cancer tissues compared with normal tissues." (PMID 40182048, 2025). "Second, the role of PSMD11 and PSMD14 in pancreatic cancer metastasis and prognosis, and their potential value in individualized therapy, merit further exploration." (PMID 40182048, 2025). "In this study, we verified that the expression of the proteasome protein PSMD11 and the deubiquitinating enzyme PSMD14 in pancreatic cancer was increased in PDAC tissues." (PMID 40182048, 2025). "Our analysis revealed significant upregulation of PSMD11 and PSMD14 in several tumors, including pancreatic cancer." (PMID 40182048, 2025). "Knockdown of PSMD11 and PSMD14 significantly inhibited the proliferation, migration, and invasion ability of pancreatic cancer cells." (PMID 40182048, 2025). "The effects of PSMD11 and PSMD14 on the malignant biological behaviors of pancreatic cancer cells, such as proliferation, migration and invasion, were investigated by in vitro experiments." (PMID 40182048, 2025). "Therefore, both PSMD11 and PSMD14 expression may serve as prognostically relevant markers for pancreatic cancer." (PMID 40182048, 2025). "Notably, we further analyzed the correlations between PSMD11 and PSMD14 expression and the prognosis of patients with pancreatic cancer in the TCGA and GSE28735 databases and divided the tumor samples into high- and low-expression groups according to the optimal segmentation point." (PMID 40182048, 2025). "In addition, bioinformatics analysis of human blood samples revealed that PSMD11 could be used as a novel biomarker for pancreatic cancer progression, but the mechanism of its development was not further investigated." (PMID 40182048, 2025).
pancreatic ductal adenocarcinoma (5 papers, 2022 to 2025). An infiltrating adenocarcinoma that arises from the epithelial cells of the pancreas. "Based on the information collected for our pancreatic ductal adenocarcinoma patients and immunohistochemical staining on their pathological sections, we showed that PSMD11 and PSMD14 were mainly expressed in the cytoplasm." (PMID 40182048, 2025). "In pancreatic ductal adenocarcinoma patients, high levels of PSMD6, PSMD9, PSMD11, and PSMD14 are associated with a lower rate of survival." (PMID 36934426, 2023). "In another study, the expression of PSMD6, PSMD9, PSMD11, and PSMD14 was significantly associated with a decreased chance of survival in patients with pancreatic ductal adenocarcinoma." (PMID 37349676, 2023). "PSMD11 and PSMD14 are highly expressed in pancreatic ductal adenocarcinoma tissues and are correlated with the degree of malignancy of pancreatic ductal adenocarcinoma; thus, PSMD11 and PSMD14 can be used as potential prognostic biomarkers and therapeutic targets for PDAC patients." (PMID 40182048, 2025). "This study further clarified the role of PSMD11 and PSMD14 in the occurrence and development of pancreatic ductal adenocarcinoma." (PMID 40182048, 2025). "Analysis of the patients’ clinical data revealed that the expression of both PSMD11 and PSMD14 was significantly correlated with lymph node metastasis, TNM grade, degree of differentiation, and poor prognosis in pancreatic ductal adenocarcinoma patients." (PMID 40182048, 2025). "In this study, bioinformatics analysis revealed the expression of PSMD11 and PSMD14 in pancreatic ductal adenocarcinoma, which can be used as biomarkers for the prognosis of patients with PDAC." (PMID 40182048, 2025). "Bioinformatics analysis revealed that the expression levels of PSMD11 and PSMD14 mRNAs were significantly higher in pancreatic ductal adenocarcinoma (PDAC) tissues than in normal pancreatic tissues and that this high expression was correlated with a poor prognosis in patients with PDAC." (PMID 40182048, 2025).
breast carcinoma (4 papers, 2009 to 2017). "In this context, Deng and colleagues demonstrated that the expression of six proteasome subunits including PSMA1, PSMB5, PSMD1, PSMD2, PSMD8 and PSMD11 was increased over three-fold in breast cancer tissues when compared to adjacent normal tissues." (PMID 27966459, 2017). "PSMD11 was reported to be up-regulated in breast cancer cells." (PMID 25872475, 2015). "Moreover, PSMD11 was over-expressed in breast cancer tissue compared to adjacent normal tissue." (PMID 26044366, 2015).
epilepsy (2 papers, 2023 to 2025). A brain disorder characterized by episodes of abnormally increased neuronal discharge resulting in transient episodes of sensory or motor neurological dysfunction, or psychic dysfunction. "Experimental evidence from rodent epilepsy models reveals that hippocampal Psmd11 expression undergoes coordinated regulation through lncRNA Peg13-mediated molecular interactions." (PMID 40791576, 2025). "The resultant suppression of epileptogenic processes highlights the Peg13/miR-490-3p/Psmd11 axis as both a disease-promoting network and a viable therapeutic target for seizure disorders." (PMID 40791576, 2025). "The expression of PSMD11 was down-regulated in the hippocampus of epileptic mice, and the lncRNA Peg13 was shown to up-regulate PSMD11 in a miR-490-3p-dependent manner, thereby inactivating the Wnt/β-catenin pathway and relieving epilepsy progression in mice." (PMID 37349676, 2023).
gastric cancer (2 papers, 2022 to 2025). A primary or metastatic malignant neoplasm involving the stomach. "High expression of PSMD11 is significantly correlated with overall survival in patients with gastric cancer." (PMID 40182048, 2025).
liver cancer (2 papers, 2015 to 2025). An epithelial or non-epithelial malignant neoplasm that arises from the liver. "It has been reported that PSMD11 affects liver cancer progression by regulating CDK4 expression and thus affects liver cancer." (PMID 40182048, 2025).
lung carcinoma (2 papers, 2024 to 2025). "In lung carcinoma A549 cells, PSMD11 overexpression promotes proliferation, migration, invasion, and xenograft growth, while also altering immune-cell infiltration within the tumor microenvironment." (PMID 41268558, 2025). "Overexpression of PSMD11 enhanced proliferation, migration, invasion, and tumor growth of lung carcinoma cell line A549, while PSMD11 knockdown diminished proliferation, migration, invasion, and tumor growth of lung carcinoma cell line PC9." (PMID 38859698, 2024).
leukemia (1 paper, 2019). A malignant (clonal) hematologic disorder, involving hematopoietic stem cells and characterized by the presence of primitive or atypical myeloid or lymphoid cells in the bone marrow and the blood. "Many research demonstrated the role of CBLB in leukemia, while PSMC5 and PSMD11 were only reported to be involved in cancer development in very recent studies." (PMID 31874600, 2019).
melanoma (1 paper, 2025). A malignant, usually aggressive tumor composed of atypical, neoplastic melanocytes. "A previous study also reported that PSMD11 may play an important role in the metastasis of melanoma." (PMID 41268558, 2025).
teratoma (1 paper, 2022). A non-seminomatous germ cell tumor characterized by the presence of various tissues which correspond to the different germinal layers (endoderm, mesoderm, and ectoderm). "In our study, CARD11(caspase recruitment domain family member 11) (mutated in 18% intracranial teratomas), IRS1(insulin receptor substrate 1) (18%), PSMD11(16%), RELN(16%), RRAS2(16%), SMC1A(16%), SYNE1(16%) and ZFHX3(16%) were the tumor-related genes with the highest mutation rates in our cohort." (PMID 36457486, 2022).
urothelial bladder carcinoma (1 paper, 2023). "In urothelial bladder carcinoma, PSMD2, PSMD3, PSMD4, PSMD8, and PSMD11 genes are overexpressed." (PMID 36934426, 2023).
tumor (12 papers, 2009 to 2025). "In addition, PSMD11 has been implicated in tumorigenesis partly through the modulation of tumor metabolism–related pathways." (PMID 41268558, 2025). "Moreover, the analysis of anti-tumor drugs suggested that the AML patients exhibiting high levels of PSMD11/14 expression may benefit from utilizing mTOR inhibitors or proteasome inhibitors." (PMID 38482057, 2024). "In general, PSMD11 and PSMD14 are closely related to tumor development and poor prognosis, however few studies in the context of AML are lacking." (PMID 38482057, 2024). "This reduction in EGFR expression could elucidate the mechanism behind the observed decrease in tumor aggressiveness and increased afatinib sensitivity, highlighting the therapeutic potential of inhibiting PSMC1 and PSMD11 in LUAD." (PMID 38557672, 2024). "Conversely, expression of the proteasome 26S ATPase subunit 5 (p45/SUG) and its non-ATPase regulatory subunit 11 (PSMD11) was confined to tumour tissues; the latter subunit is known to display high activity in embryonic stem cells." (PMID 25872475, 2015). "In addition, by analyzing the expression of PSMD11 and PSMD14 in the tumor and normal groups in the three GEO cohorts, we found that all of them were significantly different and that the expression of PSMD11 and PSMD14 was higher in the tumor group than in the normal group." (PMID 40182048, 2025).
cancer (8 papers, 2019 to 2025). A tumor composed of atypical neoplastic, often pleomorphic cells that invade other tissues. "Survival analysis also established a relationship with PSM gene expression and adverse clinical outcome, where PSMA1 and PSMD11 expression were linked to more unfavorable prognosis in ≥ 30% of cancer types for both overall survival (OS) and relapse-free interval (PFI)." (PMID 36123629, 2022). "Among cancer-related genes, CARD11(18%) and IRS1(18%) were the most common somatic mutated genes, followed by PSMD11, RELN, RRAS2, SMC1A, SYNE1 and ZFHX3, and the mutation rates of the latter six genes were all 14%." (PMID 36457486, 2022). "Our previous study have shown that the PSMD11 protein was an important survival factor for cancer cells except for its key role in regulation of assembly and activity of the 26S proteasome." (PMID 33517884, 2021). "Meanwhile, it was found that depletion of PSMD11 could induce massive apoptosis in MEFs, further indicating that PSMD11 was a significant survival factor for cells, whether it could be targeted to treat cancer deserve further investigation." (PMID 33517884, 2021). "Additionally, PSMD11 protein was also found to be an important survival factor for cancer cells." (PMID 33517884, 2021). "Notably, the 26S proteasome non-ATPase regulatory subunit 11 (PSMD11) has been identified as an important survival factor for cancer cells." (PMID 40182048, 2025). "In conclusion, the comprehensive pan-cancer analysis presented here demonstrated that several PSM genes (e.g. PSMA1, PSMB4-5, PSMB8-10, PSMD2, PSMD4, PSMD11, PSME1-3, and PSMG3) may be putative biomarkers for determining prognosis and choice of treatment for different cancer types." (PMID 36123629, 2022).
neurological disease (2 papers, 2016 to 2017). "Some downregulated proteins such as DPYSL2, TPI1, ALDH, and UCHL1 were found to play critical roles in the neurological disease and PSMA1, PSMA3, PSMC2, PSMD11, and UCHL1 in protein homeostasis." (PMID 27857231, 2016).
PSMD11 also shares sentences with these, for which no sentence is quoted: Parkinson disease (3 papers); Alzheimer disease (2); lung adenocarcinoma (2); amyotrophic lateral sclerosis (1); autism (1); bladder cancer (1); cervical cancer (1); cognitive decline (1); Epstein-Barr virus infection (1); frontotemporal dementia (1); hepatocellular carcinoma (1); lymph node metastasis (1); neurodegenerative disease (1); renal carcinoma (1); serous ovarian cancer (1).